TTF1 (transcription termination factor 1)
Diseases named in the same sentence as TTF1 in open-access papers (continued):
Sharing a sentence is not in itself a finding about the gene and the disease.
lung adenocarcinoma (continued). "TTF-1 expression in lung adenocarcinoma has been thoroughly described and is considered a specific marker of lung adenocarcinoma." (PMID 24743427, 2014). "TTF-1 amplification, on the other hand, has been detected in both lung adenocarcinomas (18.9%) and squamous cell carcinomas (20.1%) and correlated significantly with the presence of KRAS mutations in the adenocarcinoma subset." (PMID 25594059, 2014). "To further characterize these tumors, we stained the tissues with two antibody combinations used by pathologists to differentiate lung adenocarcinomas (Napsin A + TTF1) and squamous cell carcinomas (p63+CK5)." (PMID 24324581, 2013). "Our present study demonstrates that the positive detection rates of survivin, hTERT, CK-7 and TTF-1 in the PB of advanced lung adenocarcinoma patients were 41.18, 61.76, 41.18 and 35.29%, respectively." (PMID 23599802, 2013). "The present study aims to detect the expressions of the thyroid transcription factor 1 (TTF-1) mRNA and protein in Xuanwei lung adenocarcinoma line (XWLC-05)." (PMID 23514941, 2013). "Thyroid transcription factor-1 (TTF-1) is a transcription factor that is expressed in approximately 75% of lung adenocarcinoma." (PMID 23706092, 2013). "We also investigated the relationship of TTF-1 with Ki-67 protein and analyzed the prognostic value of the TTF-1 protein in Xuanwei lung adenocarcinoma patients." (PMID 23514941, 2013). "Functionally, TTF-1 induced ROR-1 is necessary to sustain the EGFR signaling pathway in lung adenocarcinoma cell lines." (PMID 23922984, 2013). "The expressions of TTF-1 and Ki-67 was detected in 96 resected cases of Xuanwei lung adenocarcinoma by immunohistochemistry from January 2008 to March 2012." (PMID 23514941, 2013). "In conclusion, we used quantitative real-time RT-PCR to detect survivin, hTERT, CK-7 and TTF-1 mRNA expression levels in PB samples of advanced lung adenocarcinoma patients." (PMID 23599802, 2013). "TTF-1 is expressed in 72% of adenocarcinomas of the lung and can be a useful marker in identifying lung tissue as a primary origin of metastases, for instance to the breast." (PMID 23675755, 2013). "We also investigated immunohistochemically the expressions of TTF-1 and Ki-67 in Xuanwei lung adenocarcinoma, located in southwestern Chinese province of Yunnan." (PMID 22940844, 2012). "In the present study expression of IMP3 was correlated with expression of TTF-1 and Napsin A, histological subtype and clinical stage of lung adenocarcinoma." (PMID 23190601, 2012). "TTF-1 is primarily expressed in type II pneumocytes and Clara cells and frequently expressed in lung cancer cells, including lung adenocarcinoma cells." (PMID 22111550, 2012). "We also investigated immunohistochemically the expression of TTF-1 and Ki-67 in 62 resected cases of Xuanwei lung adenocarcinoma." (PMID 22940844, 2012). "TTF-1 has been used as an immunohistochemical marker for primary lung adenocarcinoma, despite recent reports of occasional aberrant TTF-1 staining in tumors from other primary sites." (PMID 22263108, 2012). "Combination of TTF-1 and Napsin A highly improved sensitivity and specificity for diagnosing lung adenocarcinoma." (PMID 23190601, 2012). "NK2-related homeobox transcription factor Nkx2-1 (also called Ttf-1 or Titf1) has been identified as a candidate suppressor of malignant progression in lung adenocarcinoma." (PMID 22952714, 2012). "Three different markers, Sp-A, Sp-B and TTF-1, are currently used for the differential diagnosis of primary lung adenocarcinoma." (PMID 12698189, 2003). "Additionally, the combined detection of MUC5B and TTF-1 can greatly improve the accuracy of detecting lung adenocarcinoma by distinguishing different cancer cell types." (PMID 40655139, 2025). "In contrast, the lung adenocarcinoma showed neoplastic cells with abundant vacuolated/eosinophilic cytoplasm, prominent nucleoli, and TTF‐1 immunoreactivity, findings that could be seen in ROS‐1 rearranged lung adenocarcinoma." (PMID 40028792, 2025).
lung adenocarcinoma (continued). "TTF-1 and NapsinA are the commonly used immunohistochemical indicators of lung adenocarcinoma." (PMID 39928773, 2025). "Most patients had an initial lung adenocarcinoma except one who had an adenosquamous carcinoma and one who had a combined small cell carcinoma with an adenocarcinoma component at diagnosis; all tumors were TTF-1–positive." (PMID 41256964, 2025). "Moreover, to determine the tumor properties of malignant transformed cells, we performed immunohistochemical (IHC) using the lung squamous cell carcinoma (LUSC) marker P63 and the lung adenocarcinoma (LUAD) marker TTF‐1." (PMID 40583191, 2025). "TTF-1 and NapsinA manifest positivity in cases of lung adenocarcinoma." (PMID 40008002, 2025). "Furthermore, approximately half of the cases harbored EGFR mutations (3/7, 43%), suggesting that the double-positive cases for HNF4α and TTF-1 were derived from TRU-type lung adenocarcinomas." (PMID 38710944, 2025). "The paraneoplastic and metabolic consequence of lung adenocarcinoma (especially with high hormonal signal, e.g., TTF-1 expression) may be more systemic and fatal than tumor-related symptoms." (PMID 39767631, 2024). "Clinically, CK7 and TTF-1 are typical IHC markers for lung adenocarcinoma." (PMID 38608841, 2024). "Only half of the lung adenocarcinoma tumors in this study were positive for TTF‐1." (PMID 38164123, 2024). "Moreover, TTF1 is one of the best immunohistochemical biomarkers in the diagnosis of carcinomas of lung origin, especially lung adenocarcinoma." (PMID 38276630, 2024). "In cases of lung adenocarcinoma, under malignant conditions NapA may be regulated by TTF-1, where low levels of NapA lead to TGF-β induced neoplastic cell proliferation." (PMID 38994972, 2024). "In addition, lung adenocarcinoma has tumor cells positive for TTF-1 with a positive predictive value of >90%.9,10 In our case, the tumor cells were positive for TTF-1 and Napsin A, and their expressions were consistent with lung adenocarcinoma." (PMID 39176211, 2024). "Patient#A was a 69-year-old male, former smoker, treated for a lung adenocarcinoma TTF1+ without EGFR, KRAS, or BRAF mutation or ALK or ROS1 translocation but an expression of 100% of PDL1 on the tumor cell." (PMID 37370798, 2023). "TTF-1 sensitivity in lung adenocarcinoma was slightly lower than previously reported sensitivity using paraffin-embedded material, which could be due to a reduction in intranuclear TTF-1 antigen exposure in the cytocentrifuged preparations." (PMID 37675165, 2023). "Gastroscopic biopsy pathology showed: adenocarcinoma in the fundus near the cardia, immunohistochemistry CDX2(−), CK20(−), CK7(+), NapsinA(+), TTF-1(+), Villin(−), and lung adenocarcinoma metastasis was considered in combination with medical history and immunohistochemistry." (PMID 37695388, 2023). "In lung adenocarcinoma, TTF1 and BerEP4 positivity confirmed lung origin." (PMID 36938247, 2023). "Patient#B was a 53-year-old male, current smoker, with a lung adenocarcinoma TTF1+ PDL1 0% without EGFR, KRAS, or BRAF mutation or ALK and ROS1 translocation but STK11 mutation." (PMID 37370798, 2023). "TTF-1 is a marker of lung adenocarcinoma, and p63 is an indicator of squamous cell cancer." (PMID 37508518, 2023). "Lung CT-guided puncture biopsy, immunohistochemistry ALK (D5F3) (−), CD56 (−), CDX2 (−), CK20 (−), CK5/6 (−), CK7 (+), EGFR (+), Ki67 (hot zone + 40%), P40 (−), TTF-1 (+), Villin (−), combined with immunohistochemistry, led to the diagnosis of adenocarcinoma of the lung." (PMID 37695388, 2023). "RNAscope may be considered for patients with clinically suspected lung adenocarcinoma but who are TTF-1- and Napsin A-negative as detected by IHC." (PMID 35027056, 2022). "ALK, EGFR, and TTF1 are commonly used to detect lung adenocarcinoma." (PMID 35546675, 2022). "Moreover, the expression of TTF-1 in lung adenocarcinoma tissue is higher than that in normal tissues adjacent to cancer." (PMID 35371324, 2022).
lung adenocarcinoma (continued). "Additionally, immunohistochemistry of lung tumor lesions formed after 6 and 10 months showed TTF-1 nuclear positivity thus confirming them to be lung adenocarcinoma." (PMID 35892161, 2022). "However, RNAscope can improve TTF1 sensitivity by 10.0% and Napsin A sensitivity by 12.5% compared with those of IHC in lung adenocarcinomas." (PMID 35027056, 2022). "In lung adenocarcinomas, high-grade nuclei, histological morphology of acinar and papillary, solid and micropapillary and TTF-1-negative expression were relative risk factors affecting SMARCA2-negative expression." (PMID 35289322, 2022). "The KEAP1 inactivating mutation is associated with the immunosuppressive phenotype and is frequently involved in TTF-1-negative lung adenocarcinoma, which was reported as deficient T-cell infiltration from the analysis of a pan-cancer T-cell-inflamed GEP." (PMID 35008669, 2021). "In addition, the number of cells positive for the lung adenocarcinoma marker thyroid transcription factor-1 (TTF-1) were significantly reduced by 32% with AT-RvD1 treatment." (PMID 34203378, 2021). "In virtue of the possibility of TTF-1 as a diagnostic or prognostic marker, a large number of retrospective studies have been conducted on the prognosis of non-small-cell lung cancer (NSCLC), especially lung adenocarcinoma." (PMID 34631891, 2021). "Napsin A and TTF-1 factors have frequently been detected in lung adenocarcinoma cases." (PMID 33912440, 2021). "The lung adenocarcinoma metastasis was composed of solid groups of tumor cells without any glandular formations and displayed cytokeratin 7 and thyroid transcription factor 1 (TTF-1) immunopositivity." (PMID 34514560, 2021). "Fetal adenocarcinoma of the lung is defined by histomorphology and only a few immunohistochemistry to differentiate between low-grade and high-grade subtypes (β-catenin) and to exclude endometriosis (TTF1 positivity for low-grade fetal adenocarcinoma)." (PMID 34977100, 2021). "Previous studies showed that, Calretinin, Wilms tumor protein 1 (WT-1), HBME-1, D2-40 (podoplanin), Carcinoembryonic antigen (CEA), Napsin-A and Thyroid transcription factor 1 (TTF-1) are immunocytochemical indicators for distinguishing malignant mesothelioma from lung adenocarcinoma." (PMID 32731396, 2020). "TTF-1-positive tumors were significant in patients with lung adenocarcinoma." (PMID 31528168, 2019). "In March 2017, a tissue biopsy showed lung adenocarcinoma that was TTF-1+, CK7+, CK5-." (PMID 31297337, 2019). "TTF-1 expression is an important prognostic indicator of lung adenocarcinoma." (PMID 31292000, 2019). "TTF-1 is a standard clinical marker of lung adenocarcinomas (ADs)." (PMID 31142791, 2019). "TTF-1 could be important for the survival of a subset of patients with lung adenocarcinomas expressing TTF-1 based on the lineage-specific dependency model." (PMID 31196060, 2019). "Results of our study demonstrated that CEA, CK7, TTF1, Calretinin and HBME1 are proper markers in the differentiation between lung adenocarcinoma and mesothelioma and can be associated with a high precision for mesothelioma and lung adenocarcinoma differentiation." (PMID 31528168, 2019). "Studies have shown that TTF-1 could play a critical role in the pathogenesis of primary lung adenocarcinoma." (PMID 30524957, 2018). "We speculated that tumor-associated macrophages may regulate TTF-1 expression by producing TGF-β and that the TTF-1/HMGA2/EFGR pathway may play a role in the carcinogenesis of lung adenocarcinoma." (PMID 29079814, 2017). "Furthermore, TTF-1, acted as a pneumocyte marker, was considered to be the single best marker for lung adenocarcinoma and had the added value to distinguish primary lung cancer." (PMID 29296178, 2017). "In addition, and as a control, we selected a pleural effusion from a 62 year old patient with metastatic TTF1 positive adenocarcinoma of the lung." (PMID 27548442, 2016).
lung adenocarcinoma (continued). "However, most of the lung adenocarcinomas and small cell carcinomas are also positive for TTF-1, making the distinction even more challenging." (PMID 25685581, 2015). "The reported sensitivity and specificity of immunohistochemical labeling for napsin A and TTF-1 for supporting the diagnosis of primary lung adenocarcinoma are controversial due to difference in case number (155 vs. 1674 cases), and tumor area (tissue block vs, tissue microarray)." (PMID 25889632, 2015). "The 2011 IASLC/ATS/ERS lung adenocarcinoma classification recommends using a single adenocarcinoma marker (TTF-1 or Napsin A) and a single squamous marker for NSCLC classification in small biopsy or cytology specimen in the absence of definitive glandular or squamous morphology to reserve tissue." (PMID 25977750, 2015). "Positive staining for Keratin 7, TTF1, or Napsin A can indicate lung adenocarcinoma." (PMID 25955027, 2015). "TTF-1 protein expression is prevalent in lung adenocarcinomas and is significantly associated with female gender, never-smoking status, presence of EGFR mutations and better overall survival." (PMID 25594059, 2014). "The original diagnosis of adenocarcinoma of the lung was dependent on TTF-1 positivity." (PMID 23533933, 2013). "TTF1 was instead expressed in thyroid carcinoma and lung adenocarcinomas." (PMID 24098684, 2013). "We used real-time reverse transcription PCR (RT-PCR) to detect survivin, human telomerase reverse transcriptase (hTERT), cytokeratin-7 (CK-7) and thyroid transcription factor 1 (TTF-1) mRNA expression levels in 68 advanced lung adenocarcinoma patients and 30 healthy patients." (PMID 23599802, 2013). "Our data suggest that the combination of survivin, hTERT, CK-7 and TTF-1 mRNA markers may provide a valuable tool for CTC detection and is associated with disease progression in advanced lung adenocarcinoma patients." (PMID 23599802, 2013). "TTF-1 has been shown to be positive in primary lung adenocarcinoma and in the majority of primary thyroid cancers; therefore, clinical presentation and the use of thyroglobulin staining may be important for the final diagnosis." (PMID 24455357, 2013). "In this study, we aimed to develop a real-time RT-PCR assay to investigate the expression of four epithelial or cancer-related mRNA markers, survivin, hTERT, CK-7 and TTF-1, in order to detect levels of CTCs in PB samples of advanced lung adenocarcinoma patients as well as from healthy controls." (PMID 23599802, 2013). "TTF-1 knockdown led to a decrease in colony formation in lung adenocarcinoma lines." (PMID 22940844, 2012). "In addition, our results showed that patients with strong immunohistochemical expression of TTF-1 were inversely correlated with Ki-67 expression in Xuanwei lung adenocarcinomas, consistent with previous results." (PMID 22940844, 2012). "We also investigated the expression of TTF-1 and Ki-67 in Xuanwei lung adenocarcinoma." (PMID 22940844, 2012). "Surfactant apoproteins, including surfactant protein-A (Sp-A) and surfactant protein-B (Sp-B) are used as markers for lung adenocarcinoma and thyroid transcription factor-1 (TTF-1) is used as a marker for lung adenocarcinoma, large cell carcinoma, small cell carcinoma and thyroid carcinoma." (PMID 12698189, 2003). "Negative TTF‐1 expression in lung adenocarcinomas has been linked to worse prognosis." (PMID 38164123, 2024). "TTF1 is used in the diagnosis of lung adenocarcinoma and may be misleading for diagnosing PSP." (PMID 32984377, 2020). "Collectively, these findings suggest that beyond the simple clinical correlation, TTF-1 might play an important role in EGFR-driven lung adenocarcinoma oncogenesis and it might be a biomarker of EGFR oncogenic addiction among patients with EGFR mutation-positive lung adenocarcinoma." (PMID 31196060, 2019).
lung adenocarcinoma (continued). "Additionally, anti-beta-arrestin-1 stained positive for all 6 metastatic lung adenocarcinoma in specimens from their metastatic sites, whereas anti-TTF1 and anti-NAPSA unambiguously stained only 2 (from patients 19 and 29) and 3 samples (from patients 22, 19 and 34), respectively." (PMID 30078843, 2018). "Immunohistochemical staining was positive for thyroid transcription factor 1 (TTF-1), cytokeratin 7 (CK7) and mucin 1 cell surface associated (MUC1), while negative for cytokeratin 20 (CK20), and CD15, thus suggesting bladder metastasis from lung adenocarcinoma." (PMID 24716732, 2014). "Interestingly, NKX2-1 (more commonly known as Thyroid Transcription Factor-1 or TTF-1), a common immunohistochemical marker of lung adenocarcinomas, was among the top 20 classification markers and had higher expression levels in lung SCC compared to HNSCC cancers." (PMID 23497426, 2013). "Specifically, positive staining for TTF-1 and cell adhesion molecule 5.2 (CAM 5.2), along with negative staining for p40, strongly supported a diagnosis of lung adenocarcinoma, distinguishing it from squamous cell carcinoma." (PMID 40698218, 2025). "Increased levels of both TTF-1 and Napsin A in both S6.KPP and C6.KPP suggests tumors produced in both models are Non-Small Cell lung cancer (NSCLC), specifically, lung adenocarcinoma." (PMID 40021683, 2025). "In lung adenocarcinoma, NKX2-1 (TTF-1) gain at 14q13.3 acts as a lineage-survival oncogene essential for tumor growth, but evidence does not support a direct relationship with immune checkpoint inhibitor response." (PMID 41303594, 2025). "In TTF-1-positive NSCLC, especially in TTF-1-positive lung adenocarcinomas, high differentiation is often observed." (PMID 39076994, 2024). "Especially, the brain tumor was a TTF-1-positive tumor, suggesting the cancer originated from a representative TTF-1-positive tumor, such as lung adenocarcinoma metastasis." (PMID 39192931, 2024). "Several studies have evaluated the prognostic role of TTF-1 in NSCLC, suggesting that TTF-1 is favourable prognostic biomarker for lung adenocarcinomas." (PMID 37775725, 2024). "While TTF‐1 expression is characteristic of lung adenocarcinoma, it should be noted that TTF‐1 is only positive in up to 80% of lung adenocarcinomas." (PMID 38164123, 2024). "TTF1, KRT7, SOX2, P63, and KRT5 are biomarkers for poor prognosis of lung adenocarcinoma and lung squamous cell carcinoma." (PMID 38248716, 2023). "The expression patterns of lung adenocarcinoma (LUAD) markers, such as thyroid transcription factor-1 (TTF-1), cytokeratin 7 (CK7), and napsin A, were maintained in PDO." (PMID 37993887, 2023). "MYBPH has been reported to be a transcriptional target of TTF-1 and inhibits ROCK1 activity to reduce cell motility and metastasis in lung adenocarcinoma cells." (PMID 35087137, 2022). "Moreover, SMARCA2 might be useful as a differential diagnostic indicator in primary lung adenocarcinoma, especially in TTF-1-negative tumors." (PMID 35289322, 2022). "The immunohistochemical markers of lung adenocarcinoma (CK7, TTF-1, Napsin A) and enteric differentiation (CDX-2, CK20, MUC2, villin) were both expressed in PEAC." (PMID 35172862, 2022). "The homeobox protein Nkx-2.1 [also known as thyroid transcription factor-1 (TTF-1)] has a role in lung development and surfactant homeostasis and is highly expressed in both small-cell lung carcinoma (SCLC) and lung adenocarcinoma." (PMID 32983988, 2020). "Lung adenocarcinoma was positive for MCK and TTF-1, and MGs showed immunoreaction for Vimentin, Desmin and SMA; Ki67 expression of classical OPA was higher than atypical OPA and MGs." (PMID 32807166, 2020).